RNU7-127P (RNA, U7 small nuclear 127 pseudogene)
Gene: Small nuclear RNA gene on chromosome 2 (236,037,250 to 236,037,311, forward strand). Ensembl gene ENSG00000238812.
Homologues: Orthologues: chimpanzee U7 (98% identical), pig U7 (76% identical). Paralogues in human: RNU7-143P (84% identical), RNU7-34P (84% identical), RNU7-55P (82% identical), RNU7-62P (82% identical), RNU7-95P (82% identical), RNU7-187P (81% identical), RNU7-50P (81% identical), RNU7-67P (81% identical), RNU7-70P (81% identical), RNU7-7P (81% identical), RNU7-88P (81% identical), U7 (81% identical), and 142 more.